TRIM8 (tripartite motif containing 8)
Diseases named in the same sentence as TRIM8 in open-access papers (continued):
Sharing a sentence is not in itself a finding about the gene and the disease.
keratitis (3 papers, 2021 to 2025). A corneal disease that is characterized by inflammation of the cornea. "TRIM8 can activate the K63-linked polyubiquitination of TAK1 to enhance the activation of NF-κB in Pseudomonas aeruginosa-induced keratitis." (PMID 37520369, 2023). "A critical role for TRIM8 in inflammatory processes has been highlighted by proof that TRIM8 has pro-inflammatory effect in keratitis induced by Pseudomonas aeruginosa, a major cause of ocular morbidity that often leads to inflammatory epithelial edema with corneal ulceration and vision loss." (PMID 33807506, 2021).
melanoma (3 papers, 2020 to 2022). A malignant, usually aggressive tumor composed of atypical, neoplastic melanocytes. "The gene expression of TRIM2 and TRIM27 was markedly higher, and the expression of TRIM7, TRIM8, and TRIM29 was significantly downregulated in melanoma." (PMID 33118318, 2020). "We used the GEPIA database to investigate the prognostic analysis of TRIM2, TRIM7, TRIM8, TRIM18 (MID1), TRIM19 (PML), TRIM27, and TRIM29 in melanoma." (PMID 33118318, 2020). "Differential expression of TRIM2, TRIM7, TRIM8, TRIM18 (MID1), TRIM19 (PML), TRIM27, and TRIM29 may play an important role in the development of melanoma." (PMID 33118318, 2020).
osteosarcoma (3 papers, 2017 to 2024). A usually aggressive malignant bone-forming mesenchymal neoplasm, predominantly affecting adolescents and young adults. "In summary, we identified two Ub/UBL genes (TRIM8 and UHRF2) that were most strongly associated with the survival of osteosarcoma patients." (PMID 38879525, 2024). "The risk heat map showed that the gene expression of ST3GAL4, TRIM8, STC2, TRPS1, and FAM207A increased from low-risk to high-risk groups, indicating that the five genes in this study were related to osteosarcoma." (PMID 35102149, 2022). "ST3GAL4, TRIM8, STC2, TRPS1, and FAM207A are high-risk genes that are involved in the occurrence and development of osteosarcoma." (PMID 35102149, 2022). "However, literature on the role of Trim8 in osteosarcoma and hypoxia is poor." (PMID 35102149, 2022). "Second, our study primarily relied on bioinformatics analysis, with validation of the differential expression of TRIM8 and UHRF2 in osteosarcoma conducted at the tissue and cellular levels." (PMID 38879525, 2024). "In our future research, we will validate the signaling pathways of TRIM8 and UHRF2 that potentially influence the phenotype of osteosarcoma through gene interference." (PMID 38879525, 2024). "TRIM8 and UHRF2 are potential prognostic genes in osteosarcoma, and these results provide insights into the roles of these genes and their implications for patient outcomes." (PMID 38879525, 2024). "Tripartite Motif Containing 8 (TRIM8) and Ubiquitin Like With PHD And Ring Finger Domains 2 (UHRF2) were screened as genes with prognostic value in osteosarcoma." (PMID 38879525, 2024). "Immunohistochemical staining for TRIM8 and UHRF2 indicated that these proteins were highly expressed in osteosarcoma tissues." (PMID 38879525, 2024). "The results showed that the expression levels of ST3GAL4, TRIM8, STC2, TRPS1, and FAM207A genes were significantly higher in the osteosarcoma cell line compared to that in the normal human osteoblasts." (PMID 35102149, 2022). "We performed qRT-PCR to detect the expression of ST3GAL4, TRIM8, STC2, TRPS1, and FAM207A genes in normal human osteoblasts (hFOB1.19) and osteosarcoma cells (MG63 and SJSA-1)." (PMID 35102149, 2022). "Accordingly, the restoration of TRIM8 levels in osteosarcoma U2OS cells stably inhibited their capability of forming colonies, confirming the anti-proliferative action of TRIM8 and suggesting its role in cell-cycle control." (PMID 29182544, 2017). "Finally, TRIM8 and UHRF2 were identified as prognostic hub genes in osteosarcoma by LASSO regression analysis (λ = lambda.1se)." (PMID 38879525, 2024). "TRIM8 and UHRF2 were confirmed to be highly expressed in osteosarcoma cell lines and tissues." (PMID 38879525, 2024). "Moreover, the differential expression of TRIM8 and UHRF2 in the normal and osteosarcoma groups was also successfully validated in cell lines by qRT-PCR and Western blotting and in human tissues by immunohistochemistry." (PMID 38879525, 2024). "TRIM8 and UHRF2 are potential prognostic genes for osteosarcoma." (PMID 38879525, 2024). "Our findings suggested that ST3GAL4, TRIM8, STC2, TRPS1, and FAM207A could be used as potential biomarkers for the prognosis of patients with osteosarcoma." (PMID 35102149, 2022). "Therefore, we suggested that ST3GAL4, TRIM8, STC2, and FAM207A genes could regulate the immune microenvironment of osteosarcoma by influencing cytokines to promote tumor growth and invasion." (PMID 35102149, 2022).
renal carcinoma (3 papers, 2017 to 2024). A carcinoma arising from the epithelium of the renal parenchyma or the renal pelvis. "Seven genes (TRIM8, TRIM11, TRIM16, TRIM24, TRIM27, TRIM32, and PML) were expressed in different renal cancer cell lines through the KM expression website." (PMID 33173411, 2020).
anaplastic thyroid cancer (2 papers, 2021 to 2022). "In colorectal cancer and in anaplastic thyroid cancer (ATC), TRIM8 seems to be associated with chemoresistance of CRC and ATC cells, respectively." (PMID 35565438, 2022). "TRIM8 expression was downregulated in anaplastic thyroid cancer tissues and suppresses cell proliferation." (PMID 33858426, 2021). "Finally, in anaplastic thyroid cancer (ATC), TRIM8 is a direct target of miR-182, which is upregulated in ATC tissue and cell lines." (PMID 35565438, 2022).
brain tumours (2 papers, 2014 to 2017). "It has been previously demonstrated that TRIM8 maps on chromosome 10q24.3 within a region mostly involved in deletions and rearrangements in brain tumours." (PMID 25277184, 2014).
colon carcinoma (2 papers, 2017 to 2021). "TRIM8 is downregulated in colon carcinoma cells due to the inhibitory action of miR-17-5p and miR-106b." (PMID 33673719, 2021). "This ultimately leads to cell proliferation reduction or block, observed also in colon cancer xenografts overexpressing TRIM8." (PMID 28327152, 2017).
hepatocellular carcinoma (2 papers, 2024 to 2025). A malignant tumor that arises from hepatocytes. "The biological effects and underlying mechanism of TRIM8 in hepatocellular carcinoma (HCC) remain unknown." (PMID 38879600, 2024).
Insulin resistance (2 papers, 2022 to 2023). Increased resistance towards insulin, that is, diminished effectiveness of insulin in reducing blood glucose levels. "Overexpression of TRIM8 exacerbates HFD-induced insulin resistance and gluconeogenes, while deficiency in RTIM8 ameliorates these phenotypes." (PMID 35806477, 2022). "Notably, in contexts of HFD-induced or genetic deficiency (ob/ob)-triggered fibrosis, insulin resistance, inflammation, and hepatic lipid accumulation, TRIM8 binds to and ubiquitinates TAK1." (PMID 37867509, 2023). "Studies have shown that TRIM8 promotes HFD-induced insulin resistance and NASH by activating JNK and p38 through TAK1." (PMID 37867509, 2023). "At the same time, TAK1 specific inhibitor 5Z-7-OX completely blocked the effect of TRIM8 on HFD-induced insulin resistance." (PMID 37867509, 2023). "Taken together, these results indicate that upregulation of TRIM8 expression aggravates hepatic insulin resistance induced by high-fat diet feeding." (PMID 37867509, 2023). "Studies have further clarified the mechanism of TRIM8 promoting insulin resistance and NASH." (PMID 37867509, 2023). "Recent studies have revealed that TRIM8 aggravates hepatic insulin resistance." (PMID 37867509, 2023). "Most importantly, interfering with the interaction between TRIM8 and TAK1 can block the effect of TRIM8 on TAK1 ubiquitination and completely reverse the effect of TRIM8 overexpression on HFD-induced insulin resistance and MAFLD phenotype." (PMID 37867509, 2023). "Consistent with the insulin resistance function, TAK1 specific inhibitor 5Z-7-OX almost completely offset the positive regulation of TRIM8 on liver weight gain, lipid accumulation and abnormal liver function." (PMID 37867509, 2023).
leukemia (2 papers, 2022 to 2024). A malignant (clonal) hematologic disorder, involving hematopoietic stem cells and characterized by the presence of primitive or atypical myeloid or lymphoid cells in the bone marrow and the blood. "Experiments in Jurkat and SUP-B15 revealed that TRIM8 knockdown decreased the proliferation of leukemia cell lines." (PMID 39224802, 2024). "Mice with TRIM8 gene knockdown in leukemia cells exhibited a significant decrease in the percentage of leukemia cells in peripheral blood, a noticeable reduction in spleen size and weight, and an overall increase in body weight." (PMID 39224802, 2024). "Further experiments demonstrated a more favorable prognosis in mice with TRIM8-knockdown leukemia cells." (PMID 39224802, 2024). "Furthermore, it revealed that the expression of TRIM8 is a contributing factor to the proliferation of leukemia cells and worsens the prognosis of cALL." (PMID 39224802, 2024). "We established a T-ALL leukemia model in C57 mice with TRIM8 knockdown leukemia cells." (PMID 39224802, 2024).
lung adenocarcinoma (2 papers, 2022 to 2025). A carcinoma that arises from the lung and is characterized by the presence of malignant glandular epithelial cells. "However, a significant association between low TRIM8 mRNA expression and poor overall survival outcomes was predicted based on published data for cohorts of patients with lung adenocarcinoma (n = 672; P = 2E–6) and stage I disease (n = 346; P = 0.0029)." (PMID 39934162, 2025). "Analyses of 68 Taiwanese patients with lung adenocarcinoma showed that patients with low TRIM8 expression experienced a significantly shorter overall survival time than did those with high TRIM8 expression (P = 0.035)." (PMID 39934162, 2025). "Our results showed that, compared with high expression, low TRIM8 mRNA expression is associated with shorter overall survival in patients with NSCLC, early-stage lung adenocarcinoma and squamous cell carcinoma." (PMID 39934162, 2025). "In this study, we first identified TRIM8 as a tumour suppressor in human lung adenocarcinoma." (PMID 39934162, 2025).
lung carcinoma (2 papers, 2022 to 2025). "This study is the first to identify the novel TRIM8-interacting protein MYOF and to clarify that TRIM8 regulates lung cancer metastasis through the K48-linked ubiquitin-mediated degradation of MYOF." (PMID 39934162, 2025). "Moreover, low expression of TRIM8 was associated with poor overall survival in both the Taiwanese and GEO lung cancer cohorts." (PMID 39934162, 2025). "The results revealed that the TRIM8 mRNA level was markedly lower in lung cancer tissues than in normal tissues." (PMID 39934162, 2025). "In this study, we employed in vivo and in vitro experiments to determine the role and regulatory mechanisms of TRIM8 in lung cancer progression." (PMID 39934162, 2025). "TRIM8 overexpression in lung cancer cells reduced MYOF expression, and restoring MYOF rescued cell migration in TRIM8-overexpressing cells." (PMID 39934162, 2025). "In summary, this study revealed that TRIM8 suppresses lung cancer cell proliferation, colony formation, migration, invasion, and metastasis." (PMID 39934162, 2025). "Cell clones with stable constitutive TRIM8 expression were established to elucidate the effects of TRIM8 expression on lung cancer progression." (PMID 39934162, 2025). "GEO profiles of 601 lung cancer tissues and 99 adjacent normal tissues revealed lower levels of TRIM8 mRNA in lung cancer tissues than in normal tissues." (PMID 39934162, 2025). "Overexpression of MYOF reversed the inhibitory effect of TRIM8 on the motility of lung cancer cells in vitro." (PMID 39934162, 2025). "The expression of TRIM8 in lung cancer tissues was lower than that in normal tissues and was negatively correlated with patient survival." (PMID 39934162, 2025). "Although TRIM8 has different functions in various cancer types, its function in lung cancer is still unclear and requires further investigation." (PMID 39934162, 2025). "Our results provide new insights into the contribution of TRIM8 to lung cancer progression, suggesting that TRIM8 is a new biomarker and a novel therapeutic target for lung cancer." (PMID 39934162, 2025). "We believe that the relationship between TRIM8 and the tumour microenvironment in lung cancer is worthy of further exploration." (PMID 39934162, 2025). "This is the first report to indicate that TRIM8 degrades its substrate, MYOF, through K48-linked ubiquitination to inhibit lung cancer cell mobility." (PMID 39934162, 2025). "We first analysed TRIM8 mRNA expression in lung cancer patients using the Gene Expression Omnibus (GEO) database (GSE19188, GSE30219 and GSE31210) to explore the role of TRIM8 in the clinical outcomes of lung cancer patients." (PMID 39934162, 2025). "Taken together, our work indicates that TRIM8 inhibits lung cancer cell motility, at least in part, through the TRIM8-MYOF-MMP axis." (PMID 39934162, 2025). "Our in vitro experiment revealed that TRIM8 could inhibit lung cancer cell growth and motility, which was reversed by TRIM8 silencing." (PMID 39934162, 2025). "Moreover, we observed that, compared with the shLacZ control, TRIM8 shifted the morphology of A549 lung cancer cells from fibroblast-like to round and dense, while TRIM8 knockdown decreased the A549 cell density and increased cell extensibility." (PMID 39934162, 2025). "Moreover, by performing Transwell assays with matrix gels, we confirmed that restoring MYOF expression rescued the invasive capability of lung cancer cells that was suppressed by TRIM8." (PMID 39934162, 2025). "Furthermore, an in vitro anchorage-dependent assay was performed to evaluate the effect of TRIM8 on lung cancer cell growth." (PMID 39934162, 2025). "Moreover, for the first time, we demonstrated that TRIM8 plays a pivotal role in suppressing lung cancer metastasis through ubiquitin-mediated degradation of MYOF." (PMID 39934162, 2025).
lung carcinoma (continued). "Furthermore, microscopy confirmed that the total tumour area in the CL1-0 and H358 lung cancer cell lines in the mock control group was much larger than that in the TRIM8 transfectant group." (PMID 39934162, 2025). "Increasing TRIM8 expression significantly inhibited the proliferation of A549, CL1-0, and H358 lung cancer cells." (PMID 39934162, 2025). "Additionally, the regulatory interactions between TRIM8 and the tumour microenvironment during lung cancer progression are not yet clearly defined, such as how M1 macrophages induce TRIM8 expression." (PMID 39934162, 2025). "However, the true role of TRIM8 in lung cancer has not been determined and requires further characterization." (PMID 39934162, 2025).
lung squamous cell carcinoma (2 papers, 2022 to 2025). "Moreover, all hazard ratios (HRs) of the univariate Cox regression analysis of the mRNA expression levels indicated the protective role of TRIM8 in the clinical outcomes of patients with NSCLC, except for patients with stage I lung squamous cell carcinoma." (PMID 39934162, 2025).
schizophrenia (2 papers, 2022). A major psychotic disorder characterized by abnormalities in the perception or expression of reality. "From a mechanistic point of view, it was shown that the transcription factor POU3F2 is involved, since TRIM8 expression levels were induced upon POU3F2 binding to a schizophrenia-associated SNP, located within the TRIM8 promoter area." (PMID 36139694, 2022). "TRIM8 has been suggested to be one of the key genes for schizophrenia etiology by regulating neural development and synaptic functions." (PMID 36139694, 2022).
Sepsis (2 papers, 2021). Sepsis is defined as life-threatening organ dysfunction caused by a dysregulated host response to infection. "Sepsis is a systemic inflammatory response induced by severe infection that leads to a high mortality rate and a role for TRIM8 in sepsis has been reported." (PMID 33807506, 2021). "TRIM8 was significantly upregulated in LPS (lipopolysaccharide) sepsis-induced acute hepatic injury (AHI), which was a direct target of miR-373-3p." (PMID 34712740, 2021). "Downregulation of LINC00472, by modulating the miR-373-3p/TRIM8, reduced sepsis-induced AHI axis and inhibited the expression levels of main pro-inflammatory cytokines as IL-6, IL-10 and TNF-α." (PMID 33807506, 2021). "Recently, studies have revealed that TRIM8 is involved in the regulation of sepsis and ALI." (PMID 34712740, 2021). "Long non-coding RNA LINC00472 and TRIM8 were found significantly upregulated in liver tissues and human liver THLE-3 cells in LPS sepsis-induced Acute Hepatic njury (AHI) in vitro, while miR-373-3p was downregulated." (PMID 33807506, 2021). "Other miRNAs that targeted TRIM8 for degradation are miR-665-3p, which attenuated Oxygen-Glucose Deprivation (OGD)-induced apoptosis and inflammation in microglial cells and miR-373-3p, which reduced sepsis-induced by acute hepatic injury (AHI)." (PMID 33807506, 2021). "Moreover, inhibition of TRIM8 by downregulation of long noncoding RNA (lncRNA) LINC00472, which served as a sponge for miR-373-3p and negatively regulated its expression, could reduce sepsis-induced expression of main proinflammatory cytokines such as IL-6, IL-10, and TNF-α." (PMID 34712740, 2021).
squamous cell carcinoma (2 papers, 2015 to 2025). A carcinoma arising from squamous epithelial cells. "In fact, recent data showed that TRIM8 low expression level correlates with nodal metastatic progression in primary larynx squamous cell carcinoma and whose expression inhibits tumour cell colony formation in vitro." (PMID 26077989, 2015). "Experimental evidence has outlined TRIM8 as one of the genes which low expression level correlates with nodal metastatic progression in primary larynx squamous cell carcinoma and whose expression inhibits tumor cell colony formation in vitro." (PMID 26077989, 2015).
breast adenocarcinoma (1 paper, 2022). "Afterwards, we checked three additional independent breast adenocarcinoma gene expression profiles (GSE21422, GSE29431, and GSE42568) to identify the expression level of TRIM8." (PMID 35368651, 2022).